NEAT1 (nuclear paraspeckle assembly transcript 1)
Diseases named in the same sentence as NEAT1 in open-access papers (continued):
Sharing a sentence is not in itself a finding about the gene and the disease.
cancer (continued). "Nuclear-enriched abundant transcript 1 (NEAT1) played a great role in diverse cancers, but the mechanism of NEAT1 in GC remains indistinct." (PMID 33336058, 2020). "Taken together, our study suggested that NEAT1 promoted 5-Fu resistance and cancer stemness by remodeling chromatin." (PMID 33168814, 2020). "Multiple studies have elaborated that in most cancer types, levels of NEAT1 seem to be elevated, and its tumor promoting effects are accepted as well." (PMID 33202380, 2020). "NEAT1 is, just like HuR, frequently upregulated in many types of cancer, where it contributes to the progression of the disease by acting as a ceRNA sponging up different miRNAs." (PMID 32340118, 2020). "The lncRNA NEAT1 is an essential architectural component of paraspeckle nuclear bodies, and plays extensive tumorigenic roles in many types of human cancers." (PMID 32843056, 2020). "Since then, the roles of NEAT1 and the paraspeckle have expanded greatly to also include the interplay between these factors and cancer chemoresistance." (PMID 33143162, 2020). "The PABPN1–NEXT–exosome pathway thus represents one possibility of how nuclear polyadenylated lncRNAs, among them also cancer-associated lncRNAs like TUG1 and NEAT1, are targeted for degradation." (PMID 32340118, 2020). "Upregulation of HAGLROS, PVT1, LINC00160, NEAT1, HCG11, and MCM3AP-AS in cancers were associated with poor clinical outcomes in patients with HCC." (PMID 33050642, 2020). "Cancer cells were identified by experienced pathologists, and NEAT1_2 expression was manually scored from “0” to “3” based on the presence and morphology of punctuated nuclear signals corresponding to paraspeckles." (PMID 31992741, 2020). "In some cases, these promote (and other times inhibit) cancer growth, resulting in NEAT1 increasing and decreasing chemoresistance in different biological contexts." (PMID 33143162, 2020). "Nuclear-enriched abundant transcript 1 (NEAT1) is an important lncRNA with known influence on carcinogenesis and tumor progression in various cancer entities." (PMID 32640630, 2020). "In triple-negative breast cancer, lncRNA NEAT1 confered the oncogenic role through modulating chemoresistance and cancer stemness." (PMID 33168814, 2020). "Given the present in vitro findings, we further evaluated the anti-cancer role of NEAT1 knockdown in vivo." (PMID 32336952, 2020). "In order to understand the importance of NEAT1 in cancer pathology, the structure and biological roles of NEAT1 and paraspeckles will be addressed." (PMID 33143162, 2020). "The nuclear-enriched abundant transcript 1(NEAT1) is an overexpressed long non-coding RNA in many human cancer types." (PMID 33308223, 2020). "Thyroid carcinogenesis can be triggered by NEAT1 (Nuclear-enriched abundant transcript 1), which is shown in various cancers." (PMID 32102500, 2020). "The lncRNA nuclear paraspeckle assembly transcript 1 (NEAT1) is an lncRNA localized to the nucleus, which has been demonstrated to act as an oncogene in various human cancers." (PMID 31964409, 2020). "As miR-590-3p was a sponge for NEAT1 and regulated its expression, we furtherly investigated the role of miR-590-3p on cancer progression and angiogenesis in ESCC." (PMID 33680941, 2020). "In breast cancer cells, NEAT1 reduces the expression of miR-448 to elevate the metastasis and invasion of cancer cells through ZEB1 up-regulation." (PMID 32664703, 2020). "LncRNA (Nuclear Enriched Abundant Transcript 1) NEAT1 contributes to enhancing the malignancy of cancer cells." (PMID 32664703, 2020). "Compared to numerous studies of lncRNA Neat1 participated in tumor progression in multiple cancer types, mechanistic studies for the roles of PSPC1 and the paraspeckle associated proteins in tumor progression is still in the infant stage." (PMID 32570949, 2020).
cancer (continued). "It is known that NEAT1 (nuclear paraspeckle Assembly Transcript 1) is overexpressed in many cancers." (PMID 33121141, 2020). "NEAT1 performs regulatory actions in the majority of cancers by influencing the growth and physiological properties of tumors." (PMID 32692721, 2020). "We also found the proliferation of radioresistant MDA-MB-231 was suppressed, which suggests that NEAT1 also involves in the cell growth of whole populations of cancer cells." (PMID 32922184, 2020). "Finally, the pathophysiological connection between Neat1 isoform expression and tumorigenesis is well-established, and our data suggest that at least some of the cancer-related network changes caused by altered Neat1 expression may be attributed to abnormal alternative splicing regulation." (PMID 32467583, 2020). "NEAT1 is often considered an oncogene in cancer because of its role in promoting proliferation, metastasis, and EMT." (PMID 33292220, 2020). "In fact the transcripts levels of NEAT1 are generally elevated in tumours leading to both isoforms of NEAT1 being characterised as a potential biomarker for cancer." (PMID 33143162, 2020). "High levels of transcripts of long non-coding lncRNAs, MALAT1 and NEAT1 (located on the long arm of chromosome 11) have been described in various cancer types including pancreatic cancer." (PMID 32493953, 2020). "LncRNA dysregulation is related to cancer progression, including RB Nuclear paraspeckle assembly transcript 1 (NEAT1) also participates in RB progression." (PMID 33281873, 2020). "The dys-regulation and malfunction of NEAT1 have been related to various cancers, including breast cancer, colorectal cancer, ovarian carcer, cervical cancer, lung cancer, etc." (PMID 33202380, 2020). "Considering the available data, NEAT1 clearly illustrates the importance of lncRNA in cancer and chemoresistance." (PMID 33143162, 2020). "Since SAHA was reported to induce apoptosis to kill the cancer cells, the NEAT1/miR-129 mediated abnormal expression of Bcl-2 served as the major cause." (PMID 32692721, 2020). "The current knowledge presents a complex picture in which NEAT1 and even the paraspeckles interact with cancer in different ways." (PMID 33143162, 2020). "LncRNA NEAT1 have been found to possess oncogenic activity and enhance the progression and malignancy of cancer cells via targeting miRs such as miR-144-3p and miR-410." (PMID 32664703, 2020). "Increasing evidence has revealed that NEAT1 is upregulated in multiple cancers and facilitates cell invasion and migration by being a sponge for miRNAs." (PMID 33267910, 2020). "The long non-coding RNA (lncRNA) NEAT1 (Nuclear Paraspeckle Assembly Transcript 1) has recently gained considerable attention as it is abnormally expressed in human diseases, including cancer and neurodegenerative disorders." (PMID 31992741, 2020). "Nuclear paraspeckle assembly transcript 1 (NEAT1) is a long non-coding RNA (lncRNA) reported to be frequently deregulated in various types of cancers and neurodegenerative processes." (PMID 32630183, 2020). "NEAT1 is responsible for several cancer clinical features: patient survival, metastasis, recurrence, stem cell-like phenotype." (PMID 33308223, 2020). "As lncRNA NEAT1 was highly expressed in OSCC cancer cells, two kinds of siRNAs were used to knock down lncRNA NEAT1 in cells." (PMID 33023572, 2020). "Nuclear-enriched abundant transcript 1 (NEAT1) has been identified as two isoforms (3.7 kb NEAT1-1 and 23 kb NEAT1-2), and it acts as an oncogene in many cancers." (PMID 33817255, 2020). "Nuclear-enriched abundant transcript 1 (NEAT1) was reported to exert great function in different cancers, including as an oncogene in GC." (PMID 33336058, 2020). "It is well identified that NEAT1 is aberrantly expressed in various cancers and displays carcinogenicity." (PMID 33680941, 2020).
cancer (continued). "As one well-identified lncRNA, NEAT1 was elucidated as a facilitative factor in the carcinogenesis and aggravation, and a reliable prognostic marker in human carcinomas." (PMID 31868202, 2020). "Dysregulation of NEAT1 promotes the progression of cancer by accelerating proliferation, migration, and evasion." (PMID 31850199, 2019). "Summarizing the literature, it becomes obvious that NEAT1 is a lncRNA highly de‐/upregulated in a variety of cancer entities, in which it primarily acts as a competing endogenous RNA (ceRNA) which sponges tumor‐suppressive microRNA (miRNA)." (PMID 30430751, 2019). "Inhibition of NEAT1 can suppress cancer cell proliferation, migration, invasion, cell cycle and metastasis." (PMID 31481527, 2019). "A recent pan‐cancer study predicts that NEAT1 is the lncRNA which has the most cancer gene targets closely followed by the lncRNA MALAT1, LINC00969, and OIP5‐AS1." (PMID 30430751, 2019). "Our findings are thus in consistent with the previous reports that the expression of NEAT1 is positively related with cancer cell proliferation." (PMID 31462890, 2019). "report an upregulation of NEAT1 in cancer tissue and NPC cell lines and showed that knockdown of this lncRNA leads to inhibited proliferation, chemoresistance, and induced apoptosis." (PMID 30430751, 2019). "NEAT1 modulates ATGL expression leading to disrupted lipolysis in HCC cells by augmenting miR‐124‐3p leading to promoted cancer progression." (PMID 30430751, 2019). "Rescue experiments in Oct4‐silenced cells show that NEAT1 overexpression is re‐establishing cancer cell proliferation." (PMID 30430751, 2019). "Although extensive research has so far shed light on the implication of NEAT1 in cancer biology and predicts promising potential for the use of this lncRNA in cancer diagnosis, prognosis, and therapy, more studies are needed toward therapeutic interventions." (PMID 30430751, 2019). "A recent pan-cancer study predicted that NEAT1 is the lncRNA which has the most cancer gene targets." (PMID 31344855, 2019). "The central molecular role of NEAT1 is an important shared feature in all cancers and indicates to the enormous potential of NEAT1 as a target in cancer therapy." (PMID 30430751, 2019). "A contribution of NEAT1 to cancer progression has recently been investigated in the following cancer types as well, that is, gastric cancer, osteosarcoma, glioblastoma, oral and esophageal carcinoma, clear cell renal carcinoma, and cervical carcinoma." (PMID 30430751, 2019). "One shared feature of the so far investigated non-cancerous diseases is a common upregulation of NEAT1 which highlights the enormous potential of this lncRNA as diagnostic biomarker in these pathologies." (PMID 30717168, 2019). "Taken together, our results suggested that NEAT1 contributed in tumorigenesis of TNBC through regulating cancer stemness and chemoresistance." (PMID 30894512, 2019). "NEAT1 again is competitively sponging miR‐98‐5p, where high miR‐98‐5p levels are inhibiting cancer cell growth, migration, and invasion on the one hand and reducing mitogen‐activated protein kinase 6 (MAPK6) levels on the other hand." (PMID 30430751, 2019). "This review aims to provide an overview of information collected thus far pertaining to NEAT1’s role in non-cancer related diseases." (PMID 30717168, 2019). "Subsequently, the group was able to prove that NEAT1 increases AKT phosphorylation via the IGFR1 pathway promoting cancer cell growth." (PMID 30430751, 2019). "The long noncoding RNA nuclear‐enriched abundant transcript 1 (NEAT1) is reportedly involved in the initiation and progression of cancers of several types." (PMID 31038819, 2019).
cancer (continued). "Despite the ambiguous definition of NEAT1 in various investigations, miRNAs and its posttranscriptional control in cancer have been unequivocally published for years." (PMID 30575330, 2019). "Altered expression levels of the long noncoding RNA (lncRNA) nuclear‐enriched abundant transcript 1 (NEAT1) have been reported in different types of cancer." (PMID 30430751, 2019). "In our study, we identified Neat1 to be a hypoxia-sensitive lncRNA in cardiomyocytes, in agreement with studies of human Neat1 in cancer cells." (PMID 31634682, 2019). "Since NEAT1 has been demonstrated to increase survival of cancer cells, the authors propose that an upregulation of HIF-responsive genes causes tumorigenesis leading to the development of Kaposi sarcoma and other KSHV-induced tumors." (PMID 30717168, 2019). "Mounting evidence suggests the role of NEAT1 as a competitive endogenous RNA and proposes its potential use as a biomarker and therapeutic target in cancer." (PMID 31627266, 2019). "Interplay of certain miRNA with NEAT1 in diverse cancer types and the corresponding modulated protein targets (arrows indicate upregulation (↑) or downregulation (↓) of the respective factor)." (PMID 30430751, 2019). "Meta-analyses demonstrate an intensive upregulation of NEAT1 in several cancer entities, resulting in an unfavorable outcome as well as a drastic decrease in overall survival, suggesting a potential role for NEAT1 as prognostic biomarker." (PMID 30717168, 2019). "This review will give an overview of the most recent findings on the lncRNA NEAT1, especially focusing on the consequences of its deregulation and its function as ceRNA in the development of cancer." (PMID 30430751, 2019). "Surprisingly, in some types of cancer, upregulation of NEAT1 and paraspeckles prevented cellular transformation and tumorigenesis." (PMID 31921848, 2019). "While Xist is involved in X-chromosome inactivation, NEAT1 plays a regulatory role in initiation and progression of cancers." (PMID 30809433, 2019). "Neat1 is widely expressed in many tissues and cells and exerts pro-proliferation effects on many cancer cells." (PMID 31243262, 2019). "Nuclear enriched abundant transcript 1 (NEAT1) is a long non-coding RNA (lncRNA) located on chromosome 11 whose abnormal expression has been identified in a number of cancers and is involved in the miR-101-3p/SOX9/Wnt/β-catenin axis." (PMID 31817513, 2019). "Function of a few lncRNAs such as Xist and NEAT1, both involved in cancer progression, have been experimentally validated." (PMID 30809433, 2019). "Similar to MALAT1, NEAT1 is also reported to be a transcriptional regulator of various genes involved in cancer progression." (PMID 30512195, 2019). "(b) Knockdown of NEAT1 results in a reduction of cancer cell growth, proliferation, migration, invasion, and an increase in apoptosis in vitro as well as in reduced tumor size and metastasis in vivo." (PMID 30430751, 2019). "The expression of the transcription factor octamer‐binding transcription factor 4 (Oct4), which has been shown to be upregulated as a stem cell factor in several cancer entities, positively correlates with NEAT1 expression in NSCLC patients." (PMID 30430751, 2019). "NEAT1 is overexpressed in various cancers, and upregulation of NEAT1 is positively correlated with the poor overall survival of these cancers." (PMID 31290116, 2019). "The oncogenic implications of NEAT1 on diversified cancers have been proved in previous relevant studies." (PMID 30575330, 2019). "Meta-analyses and other studies showed that lncRNA NEAT1 is upregulated in various cancer entities resulting in an unfavorable prognosis as well as a poor overall survival." (PMID 31344855, 2019).
cancer (continued). "The upregulation of NEAT1 negatively correlated with miR‐448 expression, which is a known inhibitor of cancer cell growth." (PMID 30430751, 2019). "The abnormal upregulation of NEAT1, a newly described lncRNA, has been observed in many cancers and play critical roles in tumorigenesis." (PMID 29788922, 2018). "As expected the expression of NEAT1 was higher in HCC tissues than in the corresponding para-cancer liver tissues." (PMID 29764424, 2018). "NEAT1 is up-regulated in various types of cancers and several studies have indicated multiple mechanisms of NEAT1 up-regulation." (PMID 29764424, 2018). "shRNA-mediated reduction of NEAT1 enhanced the in vitro radiosensitivity of cancer cell lines to radiation therapy." (PMID 30374364, 2018). "LncRNA nuclear enriched abundant transcript 1 (NEAT1) has been identified to be an oncogene to promote tumor growth and metastasis of many cancers." (PMID 29654165, 2018). "The meta-analysis results suggest the prognostic role NEAT1 in prognosis in the patients with different types of cancer." (PMID 30459529, 2018). "LncRNA nuclear paraspeckle assembly transcript 1 (NEAT1) was reported as an oncogenic lncRNA in several types of human cancers." (PMID 30053878, 2018). "Recently, NEAT1 has been shown to have oncogenic roles and to facilitate tumorigenesis in various human cancers." (PMID 29515109, 2018). "The current research on NEAT1 is still at a very early stage, but growing evidence has clearly identified NEAT1 as an attractive biomarker of cancer and an ideal candidate for lncRNA therapeutics." (PMID 30374364, 2018). "NEAT1 functions as an oncogenic factor in multiple types of cancer, including BC, and its expression is under the regulation of ERαsignaling, the miR-449b-5p/c-Met axis, and hypoxia responses." (PMID 30459529, 2018). "Apart from these strategies, targeting the upstream signaling pathways of NEAT1 or its binding partners would be another method to modulate NEAT1 expression or function in malignant tumors." (PMID 30374364, 2018). "NEAT1 is often upregulated in cancer and exhibits an oncogenic role by sponging tumor suppressive miRNAs, in turn, upregulating oncogene expression." (PMID 29702599, 2018). "The expression of NEAT1 in cancer cells is controlled by the following mechanisms: genetic alterations (such as copy number gain and gene mutation), transcription factors, DNA methylation, miRNAs and RNA-binding protein." (PMID 30374364, 2018). "The nuclear paraspeckle assembly transcript 1 (NEAT1, a long non-coding RNA) is frequently overexpressed in human tumors, and higher NEAT1 expression is correlated with worse survival in cancer patients." (PMID 30374364, 2018). "A great deal of effort has been expended to understand the functional role of NEAT1 in cancer progression." (PMID 30154460, 2018). "Animal cancer models using Neat1 KO mice also revealed contradictory effects of Neat1/paraspeckles on cancer pathogenesis." (PMID 30355755, 2018). "In order to evaluate the detailed function of NEAT1 in cancer development, NEAT1 knockdown was conducted by transfecting si-NEAT1 into A549 and H1299 cells, as confirmed by real-time PCR." (PMID 29788922, 2018). "The pooled HRs results showed that increased NEAT1 expression was positively associated with a shorter OS in patients with different types of cancers, which suggests the prognostic role of NEAT1 in predicting OS in cancer patients." (PMID 27926523, 2017). "These surprising results suggest that cancer cells can ‘hijack’ the survival principle of NEAT1 for their own good." (PMID 29254281, 2017). "No meta-analysis has been conducted to date on the correlation of NEAT1 with the survival of cancer patients." (PMID 28507281, 2017). "Given the effect of NEAT-1 on modulating the cancer cell phenotype, we evaluated the potential effect of NEAT-1 on sensitivity to gemcitabine." (PMID 28122578, 2017).